POLD2 (DNA polymerase delta 2, accessory subunit)
Diseases named in the same sentence as POLD2 in open-access papers:
POLD2 is named in the same sentence as 24 diseases in open-access papers, as found by Europe PMC text mining. Sharing a sentence is not in itself a finding about the gene and the disease. The quoted sentences say what the papers report.
breast carcinoma (5 papers, 2017 to 2024). "Several recent studies have also confirmed the high expression levels of POLD2 in the pathogenesis of various malignancies, including breast cancer, glioblastoma, multiple myeloma, and bladder urothelial carcinoma." (PMID 39341197, 2024). "To explore the function of POLD2 in TNBC, we first investigated the expression of POLD2 in normal breast and different subtypes of breast cancer (i.e., TNBC, Luminal A, Luminal B, and Her2 positive) from The Cancer Genome Atlas (TCGA) database." (PMID 36119494, 2022). "However, it should be noted that POLD2 displayed the highest expression in TNBC compared with the other subtypes of breast cancer." (PMID 36119494, 2022). "In order to prove the anti-tumor effect of Diazinon in BC, we used it to treat breast cancer cells and observed that it increased the expression of TAT while suppressing the expression of CDC6, RPA3, POLD1, and POLD2." (PMID 39334853, 2024). "TNBC, Luminal A, Luminal B, and Her2 positive breast cancers all maintain high levels of POLD2 expression compared to normal breast tissue samples." (PMID 36119494, 2022).
bladder urothelial carcinoma (4 papers, 2018 to 2024). "In addition, POLD2 is also associated with a poor prognosis in patients with bladder urothelial cancer." (PMID 36081989, 2022). "Likewise, another study found that high expression of POLD2 was associated with cisplatin-based therapy resistance in bladder urothelial carcinoma, which may contribute to the poor prognosis of patients." (PMID 36119494, 2022).
glioma (3 papers, 2010 to 2022). A benign or malignant brain and spinal cord tumor that arises from glial cells (astrocytes, oligodendrocytes, ependymal cells). "A recent study also showed that POLD2 expression was significantly elevated in glioma tissues compared with non-tumor tissues, and high expression of POLD2 was associated with shorter survival in glioma patients." (PMID 36119494, 2022). "Additionally, POLD2 has been implicated in ovarian carcinogenesis as well as poor glioma patient prognosis." (PMID 30038717, 2018). "In gliomas, a consistent pattern of chromosomal alterations were found involving altered regions which harboured seven “landscape genes” associated with patient survival, among these POLD2." (PMID 21079801, 2010).
ovarian carcinoma (3 papers, 2010 to 2022). A malignant neoplasm originating from the surface ovarian epithelium. "The network based approach identified two 7-gene functional interaction modules (31: DCLRE1A, EXO1, KIAA0101, KIN, PCNA, POLD3, POLD2; 35: DKK3, FABP3, IRF1, AIM2, GBP1, GBP2, IRF2) that are associated with prognosis of ovarian cancer patients." (PMID 27806724, 2016). "POLD2 was found to be increased in average 2.5- to almost 20-fold in moderately and poorly differentiated serous carcinomas of epithelial ovarian cancer, eventually leading to poor prognosis." (PMID 27806724, 2016). "In addition, several studies have shown that POLD2 is aberrantly expressed in multiple cancers, including ovarian carcinoma and glioblastoma." (PMID 36119494, 2022). "For example, POLD2 was highly expressed in ovarian carcinomas, and patients with high POLD2 expression had a tendency of shorter survival, suggesting that POLD2 was a predictor of the prognosis for ovarian cancer patients." (PMID 36119494, 2022). "A major finding in this study was the strong upregulation of POLD2 in PDSC compared to control tissues and other histological subgroups of ovarian carcinomas examined." (PMID 21079801, 2010).
glioblastoma (2 papers, 2022 to 2024). The most malignant astrocytic tumor (WHO grade IV). "And another study in glioblastoma stem-like cells showed that SOX2 significantly induced the expression of POLD2 by binding to the POLD2 promoter." (PMID 36119494, 2022). "showing that shRNA-based POLD2 expression knockdown inhibited glioblastoma development, indicating that developing POLD2 inhibitors may provide a potential therapeutic strategy to inhibit the progression of malignancies in future research." (PMID 36119494, 2022). "And interference of POLD2 with shRNA inhibited glioblastoma cell proliferation, cell cycle progression, invasiveness, and sensitized glioblastoma cells to chemo/radiation-induced cell death, indicating that POLD2 is a new potential therapeutic target for glioblastoma." (PMID 36119494, 2022).
oligodendroglioma (2 papers, 2023). A well-differentiated (WHO grade II), diffusely infiltrating neuroglial tumor, typically located in the cerebral hemispheres. "We observe that different genes belonging to this pathway exhibit different trends, for example genes such as POLD1(chr19), RPA2(chr1), and LIG1(chr19) loose a copy in IDH-mut oligodendrogliomas, while genes RPA3(chr19), PMS2(chr19), PCNA(chr20) and POLD2(chr7) gain a copy in IDH-wt GBM." (PMID 36918656, 2023).
serous carcinomas (2 papers, 2010 to 2016). "Except for POLD2, the serous carcinomas showed a similar transcription profile, being clearly different from CCC." (PMID 21079801, 2010). "Except for the marked upregulation of POLD2 in PDSC, the expression levels of the other mRNAs in PDSC and MDSC were similar, in agreement with a common tumourigenetic pathway for moderately and poorly differentiated serous carcinomas as previously suggested." (PMID 21079801, 2010).
bladder cancer (1 paper, 2018). "Of note, we found that ERCC2 alterations (which are recurrently found in bladder cancer) co-occur significantly with POLD2 expression (P = 0.010; data not shown), but not with CAD expression, suggesting POLD2 as putative gene of interest in future studies examining ERCC2." (PMID 30038717, 2018).
hepatoma (1 paper, 2020). "Human hepatocytes from transplanted mice showed a different gene expression profile compared to the hepatoma lines and expressed higher POLD2 and RFC1 transcripts." (PMID 32799415, 2020).
Pca (1 paper, 2023). "By combining both KEGG analysis and GO term analysis, seven genes (RNASEH2A, RFC2, RFC4, LIG1, POLD1, POLD2, and POLE4) were identified as new biomarker genes upregulated in CRPC compared to localized Pca and associated with DNA replication and DNA repair." (PMID 37950047, 2023).
uroepithelial carcinoma (1 paper, 2022). "The correlation between POLD2 expression and ICB response was validated by analyzing data from the immunotherapy cohort of uroepithelial carcinoma (IMvigor210)." (PMID 36081989, 2022).
tumor (12 papers, 2012 to 2025). "High POLD2 expression was significantly associated with advanced tumor stage, significantly shorter overall survival and progression-free survival." (PMID 36081989, 2022). "We found that in most tumor samples, these 5 MMRs gene mutations were positively correlated with POLD2 expression (p < 0.05)." (PMID 36081989, 2022). "In addition, the article investigates the correlation of POLD2 with immunomodulatory genes and immune marker sets, such as tumor mutation burden (TMB) and microsatellite instability (MSI)." (PMID 36081989, 2022). "Furthermore, our research provides insights into the underlying mechanism by which POLD2 overexpression may regulate tumor immunity." (PMID 36081989, 2022). "In TNBC, E2F1 is particularly implicated in promoting aggressive tumor characteristics through the upregulation of CCNA2, which regulates both the G1/S and the G2/M transition phases, and POLD2, which is crucial for DNA replication and repair." (PMID 41413688, 2025). "The article investigated the expression levels of POLD2 in different cancers and examined the potential impact of POLD2 in the tumor microenvironment." (PMID 36081989, 2022). "Next, we used the TIMER2 database to evaluate the correlation between POLD2 expression and tumor immune infiltration in cancer." (PMID 36081989, 2022). "Our research showed that POLD2 is a potential prognostic biomarker, which can be used for clinical tumor prognosis prediction and immunotherapy assessment." (PMID 36081989, 2022). "Using microarray, expression of POLD2 was found to be down-regulated by the exogenous overexpression of PTEN tumor suppressor." (PMID 36119494, 2022). "The prognostic impact of POLD2 on tumor patients was analyzed using clinical survival data from TCGA." (PMID 36081989, 2022). "We use the ESTIMATE algorithm to evaluate the expression of POLD2 in the tumor microenvironment through the TIMER database." (PMID 36081989, 2022). "High expression of POLD2 was also associated with poor overall survival (P = 0.019) and was significantly correlated with CAD expression in pre-treatment patient tumor samples (P = 2.44e-4)." (PMID 30038717, 2018). "CAD and POLD2 were significantly correlated in BLCA tumor samples; however, when restricted to patients administered cisplatin-based therapy, patient expressions became more tightly correlated (r = 0.45, P < 0.001 vs r = 0.61, P < 0.001, respectively)." (PMID 30038717, 2018). "POLD2 could recently be uncovered as a tumor suppressor and prognostic biomarker in distinct cancers." (PMID 36899812, 2023). "This indicates that POLD2 may play a facilitating role in tumor development in a variety of cancers." (PMID 36081989, 2022). "Then, we explored the relationship between POLD2 expression and tumor stage." (PMID 36081989, 2022). "Furthermore, tumor microenvironment analysis suggests that high POLD2 expression inhibits infiltration of CD8+ T cells and CD4+ memory T cells." (PMID 36081989, 2022). "The results indicate that the high level of POLD2 expression may be closely related to the advanced stage of the tumor." (PMID 36081989, 2022). "In the future, more basic and clinical researches based on POLD2 and tumor microenvironment may help us to optimize the clinical strategy of cancer treatment." (PMID 36081989, 2022). "This article focuses on the potential of POLD2 in tumor immunotherapy." (PMID 36081989, 2022). "This indicates that POLD2 may be used as a new tumor marker." (PMID 36081989, 2022). "Furthermore, POLD2 is also involved in tumor immune escape, which may be used as an immune checkpoint for cancer treatment." (PMID 36081989, 2022). "At the same time, we noticed that the high expression of POLD2 is also related to MYC targets v2, and the high MYC target score is related to tumor aggressiveness and poor prognosis in metastatic adenocarcinoma." (PMID 36081989, 2022).
tumor (continued). "In this study, we systematically assessed the prognostic performance of DNA replication-related genes for predicting tumor recurrence and constructed a novel and robust signature including EREG, KCTD13, MCM3AP, MCM3, POLD2, TERF2, and TP73." (PMID 33748108, 2021). "Cases with POLD2 and EXO1 expression above the tumor average had decreased survival by Log-rank." (PMID 31857847, 2019). "Third, tumor samples analyzed for drug response were solely pre-treatment samples, so determining whether systemic chemotherapy may be inducing CAD/POLD2 for adduct bypass is beyond the scope of our study." (PMID 30038717, 2018).
cancer (9 papers, 2019 to 2024). A tumor composed of atypical neoplastic, often pleomorphic cells that invade other tissues. "It was already confirmed that the occurrence of various cancers is closely linked to DNA mutations and damage repair mechanisms in which the encoding product of POLD2 also participates." (PMID 39341197, 2024). "Other studies have also demonstrated that POLD2 is highly expressed in a variety of cancers and is also associated with poor disease prognosis." (PMID 36081989, 2022). "Current studies have found an association between POLD2 and the development of a variety of cancers." (PMID 36081989, 2022). "In our study, pathway enrichment analysis demonstrated that the high expression of POLD2 is associated with abnormal pyrimidine and purine metabolism, which play a vital role in the occurrence and development of cancer in the early stage." (PMID 36081989, 2022). "Meanwhile, this study also confirmed that overexpression of POLD2 may be associated with a poorer prognosis of cancers, which exhibit a high degree of resemblance to the findings obtained in our study." (PMID 39341197, 2024). "Thus, the significance of the association between the occurrence and progression of cancer and POLD2 is indisputable." (PMID 39341197, 2024). "Since POLD2 is overexpressed in a variety of human cancers and is associated with worse survival, it may serve as a potential target for cancer management." (PMID 36081989, 2022). "These indicate that the high expression of POLD2 is associated with the poor prognosis of cancer patients, and it may result in a lower survival rate of patients." (PMID 36081989, 2022). "We evaluate the expression of POLD2 in a variety of cancers and normal samples to study the relationship between POLD2 and cancer." (PMID 36081989, 2022). "POLD2 expression is upregulated in various cancers, but little is known about how the expression of POLD2 is regulated." (PMID 36119494, 2022). "In summary, the results of the present study clarify the strong correlation between POLD2 expression and the prognosis of various cancers." (PMID 36081989, 2022). "When chromosomal translocations occur, normal proto-oncogenes are transformed into oncogenes that cause malignant transformation of cells, that is why we believe that POLD2 has the potential to act as a cancer marker." (PMID 36081989, 2022). "First of all, though we have obtained some meaningful insights into POLD2 in human cancer from data mining, it will be beneficial to clinical applicability if these findings are verified by cell or animal experiments." (PMID 36081989, 2022). "We examined the relationship between POLD2 expression and immune checkpoint genes, and then further analyzed the correlation with the degree of immune infiltration in human cancers." (PMID 36081989, 2022). "In most cancers, most chemokine receptors are negatively correlated with the expression of POLD2 (p < 0.05)." (PMID 36081989, 2022). "Many researches point out that the abnormal expression of POLD2 is frequently related to the occurrence, development or metastasis of human cancer." (PMID 36081989, 2022). "Overall, this work provides evidence to elucidate the immunotherapeutic role of POLD2 in cancer and contributes to further functional experimental studies of cancer therapy." (PMID 36081989, 2022). "Next, we use Kaplan-Meier survival curve analysis to evaluate the impact of POLD2 on the prognosis of different cancers." (PMID 36081989, 2022). "In this study, a pan-cancer analysis of POLD2 was performed, and the results showed that the upregulation of POLD2 expression is associated with the poor prognosis of many tumors." (PMID 36081989, 2022). "In the analysis of 23 immunosuppressive genes, PVRL2 was positively correlated with the expression of POLD2 in most cancers (p < 0.05)." (PMID 36081989, 2022). "It was found that as the cancer stage increased, the expression level of POLD2 in ACC, HNSC, LUAD, and TGCT increased (p < 0.05)." (PMID 36081989, 2022).
cancer (continued). "We first compared the expression of POLD2 in cancer and paraneoplastic tissues based on TCGA databases." (PMID 36081989, 2022). "Our observations are of particular interest with respect to human cancers, which commonly elevate POLD2 and POLD3 levels, perhaps to compensate elevated levels of replication stress." (PMID 34226278, 2021). "Via bioinformatics technology, POLD2 had been demonstrated to be significantly overexpressed in most tumors and may be a molecular biomarker for pan-cancer prognosis likewise." (PMID 39341197, 2024). "And as the cancer stage progresses, the expression of POLD2 shows an upward trend in most cancers." (PMID 36081989, 2022). "Therefore, our work clarifies the potential role of POLD2 in cancer immunology and its prognostic value to human cancer." (PMID 36081989, 2022). "Discussion: In conclusion, POLD2 may be a molecular biomarker for pan-cancer prognosis and immunotherapy." (PMID 36081989, 2022). "We researched the correlation of 46 immune activation genes with POLD2 in pan-cancer." (PMID 36081989, 2022). "In comparison to the comprehensive investigation of POLD2, POLR2G received comparatively less attention in cancer occurrence and progression." (PMID 39341197, 2024). "The results show that in most cancers, the expression of chemokine CCL27 and POLD2 are positively correlated (p < 0.05)." (PMID 36081989, 2022). "In most cancers, CD86, TNFSF14, KLRK1, CD48, CD40LG, CD28, C10orf54, ENTPD1, CXCL12, and POLD2 are negatively correlated (p < 0.05)." (PMID 36081989, 2022). "Thus, E2F1 could promote cancer proliferation via upregulating POLD2 expression in TNBC, indicating that the E2F1-POLD2 signaling pathway is a driver of TNBC proliferation and could be a potential therapeutic target for the treatment of TNBC." (PMID 36119494, 2022). "Obviously, POLD2 can provide some new ideas for cancer treatment, but we have not been well explored for the specific relationship between high POLD2 expression and carcinogenesis, therefore, further study of the mechanism of POLD2 oncogenic effect has some significance for cancer treatment." (PMID 36081989, 2022).
infection (2 papers, 2020 to 2021). The state of being infected such as from the introduction of a foreign agent such as serum, vaccine, antigenic substance or organism. "Knocking down POLD2 impaired TYLCV DNA replication in local infection assays, whereas knocking down POLE2 enhanced viral accumulation both locally and systemically." (PMID 33986276, 2021). "Our data suggest that the accessory components (RFC2, RFC3, RFC5, PCNA), polymerases (POLD1, POLD2, POLD3, POLE, POLE2, POLE4), and ligase LIG1, were downregulated during infection, for which the downregulation of RFC5, POLD1, POLD2, POLD3, POLE, and LIG1 was CagA-related." (PMID 33339161, 2020). "REV3 silencing did not affect viral accumulation in local infection assays, in sharp contrast to POLD1 or POLD2 silencing, indicating that DNA polymerase ζ is not required for geminiviral replication." (PMID 33986276, 2021).
degenerative diseases (1 paper, 2010). "This suggests that any candidate STEPs for POLD2, which may cause a change in splicing efficiency leading to differential protein expression, might affect the efficiency of DNA repair and over a prolonged period affect the risk of various degenerative diseases." (PMID 20948966, 2010).
neurological disease (1 paper, 2017).
POLD2 also shares sentences with these, for which no sentence is quoted: Fanconi anemia (2 papers); colon cancer (1); colorectal cancer (1); heart failure (1); medulloblastoma (1); melanoma (1); multiple myeloma (1); triple-negative breast carcinoma (1).